CLDN1 (claudin 1)
Diseases named in the same sentence as CLDN1 in open-access papers (continued):
Sharing a sentence is not in itself a finding about the gene and the disease.
lung adenocarcinoma (continued). "One study demonstrated that CLDN-1 expression correlated with Ras and epidermal-growth-factor-receptor (EGFR) expression suggesting the involvement of the latter two signaling pathways in the regulation of CLDN-1 in lung adenocarcinoma." (PMID 31952355, 2020). "Studies showed that the invasive ability of HOP62 lung adenocarcinoma cells is increased by knockdown of endogenous expression of CLDN-1." (PMID 31952355, 2020). "Immunohistochemical staining for these genes in samples from 81 cases of lung adenocarcinoma demonstrated the expressions of CLDN1 and CLDN10 were correlated with overall survival of patients with lung adenocarcinoma." (PMID 23591077, 2013). "Moreover, CLDN1 is correlated with a poor prognosis of oral squamous cell carcinoma and lung adenocarcinoma." (PMID 36672179, 2023). "Doxorubicin resistance was also reported in lung adenocarcinoma cells, where CLDN1 is speculated to inhibit the penetration of anticancer drugs into the target area." (PMID 36672179, 2023). "Our results revealed that CLDN1 is a metastasis suppressor in lung adenocarcinoma." (PMID 32754286, 2020). "Given that TSA activated CLDN1 expression in CLDN1low lung adenocarcinoma cells and CLDN1high cells were more sensitive to cisplatin, TSA may promote cisplatin-induced cell death in CLDN1low cancer cells." (PMID 32754286, 2020). "Lung adenocarcinoma patients with CLDN1 expression live longer, which may be a result of metastasis suppression and/or sensitization of cancer cells to chemotherapy." (PMID 32754286, 2020). "CLDN1 correlates with poor prognosis in lung adenocarcinoma." (PMID 32824620, 2020). "Based on our results, the CLDN1-SLUG axis repressed lung adenocarcinoma progression, we investigated whether patients with an intact CLDN1-SLUG axis lived longer." (PMID 32754286, 2020). "The mRNA level of CLDN1 in A549 cells derived from lung adenocarcinoma, RERF-LC-AI cells derived from squamous cell carcinoma, IA-LC cells derived from large cell carcinoma, and WA-hT cells derived from small cell carcinoma were higher than that in normal tissue." (PMID 32824620, 2020). "Interestingly, Claudin-1 was highly stained in lung squamous carcinoma and slightly stained in lung adenocarcinoma compared with adjacent tissues." (PMID 30874545, 2019). "For instance, it has been reported that CLDN1 is a metastasis suppressor for lung adenocarcinoma and that a lack of CLDN1 expression is associated with poor patient prognosis." (PMID 30349422, 2018). "Our observation that protein level of Claudin-1 was decreased in RBFOX3-depleted A549 human lung adenocarcinoma cells prompted us to ask whether expression of RBFOX3 correlates with that of CLDN1 in human lung tissue." (PMID 28126724, 2017). "These authors further determined that claudin-1 expression in these cells was partly driven by protein kinase C. On the other hand, low expression of claudin-1 in lung adenocarcinoma was an indicator of increased metastasis, and knockdown enhanced invasiveness." (PMID 26901232, 2016). "Our study suggested that the expression of claudin 1(p = 0.105) and claudin 10(p = 0.027) may fuction as cancer cell invasion and metastatic suppressor in lung adenocarcinoma through c-fos signal pathway." (PMID 23591077, 2013). "Low CLDN1 gene expression was correlated with shorter overall survival in lung adenocarcinoma." (PMID 20805891, 2010). "Low CLDN1 expression in response to TNF-α is regulated by the PKC/iPLA2/PGE2/PPAR signaling cascade and is associated with lung adenocarcinoma rather than lung squamous cell carcinoma, whereas increased CLDN1 expression is associated with a better prognosis and tumor suppressive activity." (PMID 36620607, 2022). "Finally, it has been suggested that CLDN1 could be a predictive marker of chemotherapy response for patients with lung adenocarcinoma." (PMID 36291810, 2022). "Therefore, a drug which can reduce CLDN1 expression may be a novel chemosensitizer for lung adenocarcinoma." (PMID 32824620, 2020).
lung adenocarcinoma (continued). "To confirm that CLDN1 expression is a positive predictor for patients who respond well to chemotherapy, we analyzed the clinical correlation between CLDN1 expression and survival of lung adenocarcinoma patients who had received chemotherapy using the KM plotter website." (PMID 32754286, 2020). "Importantly, CLDN1 expression was downregulated and correlated with the downregulated expression of EPHB6 in stage IV lung adenocarcinoma, suggesting that CLDN1 may correlate with EPHB6 expression and be a metastasis suppressor." (PMID 32754286, 2020). "CLDN1 represses tumorigenesis and CSC properties and sensitizes lung adenocarcinoma to chemotherapy drugs in vivo." (PMID 32754286, 2020). "CLDN1 represses the CSC phenotype and sensitizes lung adenocarcinoma cells to chemotherapy drugs in vitro." (PMID 32754286, 2020). "Overexpression of CLDN1 and CLDN10 indicates a favorable prognosis for overall survival in some patients with lung adenocarcinoma." (PMID 23591077, 2013). "CLDN1 was a transcriptional activator of OCLN, and was also reported as not only a metastasis suppressor but also a possible prognostic predictor for lung adenocarcinoma." (PMID 24369726, 2013). "Expression of Cldn1 was demonstrated in PTC, papillary microcarcinoma primary tumors, and lymph node metastases and is assumed to be a prognostic factor for patients with lung adenocarcinoma." (PMID 31825142, 2020). "A tight-junction protein, Claudin 1 (CLDN1), is a metastasis suppressor in lung adenocarcinoma." (PMID 32754286, 2020). "We found that PMTPV, a short peptide, which mimics the structure of second extracellular loop (ECL2) of CLDN1, can reduce the protein level of CLDN1 without affecting the mRNA level in A549 cells derived from human lung adenocarcinoma." (PMID 32824620, 2020). "Next, we investigated whether there is a clinical connection between CLDN1 and RUNX3 expression with respect to the survival of patients with lung adenocarcinoma." (PMID 32754286, 2020). "We recently reported that claudin-1 (CLDN1), CLDN2, and occludin, components of tight junctions (TJs), decrease chemosensitivity to doxorubicin (DXR), an anthracycline anticancer drug, in 3D-cultured lung adenocarcinoma A549 cells." (PMID 31551535, 2019). "Four genes (MMP-2, c-fos, claudin 1 (CLDN1) and claudin 10(CLDN10)) were correlated with the results of microarray and real time RT-PCR analyses for the gene-expression data in samples from 41 patients with lung adenocarcinoma." (PMID 23591077, 2013). "Mechanistically, CLDN1 appears to suppress tumor dissemination by downregulating zinc finger transcription factors through inhibition of the ERK1/2 (extracellular signal-regulated kinase) signaling pathway, thereby limiting the migratory potential of lung adenocarcinoma cells." (PMID 40687428, 2025). "Therefore, CLDN1 and RUNX3 are good prognostic markers for lung adenocarcinoma." (PMID 32754286, 2020).
melanoma (29 papers, 2008 to 2025). A malignant, usually aggressive tumor composed of atypical, neoplastic melanocytes. "The mechanism underlying these observations is that CLDN1‐expressing melanoma cells and CLDN1‐expressing brain ECs form homotypic CLDN1‐CLDN1 interactions, which strongly bind tumor cells to ECs." (PMID 32761606, 2021). "Studies have reported that PKC promotes melanoma cell motility through regulation of Claudin-1, a member of integral membrane proteins associated with tight junctions and the maintenance of cellular polarity." (PMID 25830567, 2015). "For example, in colon, oral squamous cancer and melanomas, the subcellular localization of claudin 1 in cytoplasm has been associated with tumor progression." (PMID 26633531, 2015). "An additional effect of PKC on melanoma was recently underlined by a study of the aberrant expression of claudin-1 in melanoma." (PMID 18442364, 2008). "Several markers can serve as indicators of melanoma phenotype changes, such as Snai1, N-cadherin, and Cldn1." (PMID 39796281, 2025). "The introduction of CLDN1 into melanoma brain metastatic cells expressing low levels of CLDN1 has been shown to suppress their metastatic phenotype." (PMID 39367275, 2024). "In melanoma, claudin-1 is abnormally expressed in the cytoplasm of malignant cells and not in the cell membrane." (PMID 34808689, 2022). "Overexpression of Claudin-1 directly contributed to melanoma cell invasion, while Claudin-1 knockdown inhibited invasion, which further supports the findings in this study." (PMID 35432533, 2022). "Another protein trafficking dysregulation in melanoma and TC is related to claudin-1: Its cytoplasmic localization is reported in invasive forms of melanoma, whereas claudin-1 nuclear localization is found in benign nevi." (PMID 33578751, 2021). "Expression levels of CLDN1 in clinical samples of benign nevi expressed significantly higher levels of CLDN1 than melanoma metastases." (PMID 32761606, 2021). "In one interesting in vitro study, melanoma cells transfected with NLS-claudin-1 vector showed significant nuclear localization of claudin-1, but still had transport of claudin-1 to the cytoplasm." (PMID 33578751, 2021). "This shows that reduction in CLDN-1 supports tumor progression and metastasis and that CLDN-1 can be used as a prognostic predictor for melanoma patients with increased risk of brain metastasis." (PMID 31952355, 2020). "When melanoma cells transfected with CLDN-1, it increased the secretions of matrix metalloproteinase- 2 (MMP-2) reflecting its contribution to the cell invasion process." (PMID 31952355, 2020). "In melanoma, CLDN-1 is abnormally/aberrantly expressed in the cytoplasm of malignant cells and not in the cell membrane." (PMID 31952355, 2020). "In melanoma cells, Cldn1 localized in cytoplasm as well as nucleus, with its expression in the former correlating to increased migration." (PMID 27899769, 2016). "Conversely, the over expression of claudin 1 has been reported and was shown to increase cell invasion in colon, colorectal, oral squamous cell carcinoma and melanoma." (PMID 26633531, 2015). "Similarly, different subcellular localizations of CLDN1 differentially regulate melanoma metastasis." (PMID 40959289, 2025). "Tight junction proteins regulate the paracellular transport of molecules, but the staining of a tissue microarray revealed that claudin-1 was overexpressed in melanoma and aberrantly expressed in the cytoplasm of malignant cells, suggesting a role other than transport." (PMID 38255907, 2024). "Cytoplasmic expression of claudin-1 enhances the migratory ability of melanoma cells." (PMID 35280730, 2022).
melanoma (continued). "Claudin-1 expression in the membrane, cytoplasm, and nucleus is altered in human malignancies including colon cancer, nasopharynx carcinoma, thyroid carcinoma, breast cancer, and melanoma." (PMID 35432533, 2022). "Furthermore, overexpressing CLDN1 in melanoma cells eliminated the capacity of such cells to form brain but not lung metastasis." (PMID 32761606, 2021). "The association of these membrane glycoproteins with MMP-2 activation is of particular interest because αvβ3 integrin is often highly expressed on melanoma, claudin-1 expression levels increase with increasing thickness of the primary lesion and CSPG4 is potentially a useful biomarker for melanoma." (PMID 24069584, 2013). "However, classical PKCs phosphorylate CLDN1 to induce nuclear localization in melanoma cells." (PMID 33172177, 2020). "The DOCK1 depletion-induced increase in claudin-1 inhibited cell migration and induced caspase activation and cell death, which is consistent with the previous finding that re-expression of claudin-1 causes cell apoptosis in TNBC and modulates the mobility of melanoma cells." (PMID 31717460, 2019). "After 24-h GH treatment, SK-MEL-30 human melanoma cells showed a modest but significant increase of multiple EMT-related genes including mesenchymal markers ZEB-1, SNAI1, CLDN1 and SNAI2, while the epithelial marker CDH1 was significantly downregulated." (PMID 33291663, 2020). "In melanoma patients with brain metastases, the expression of CLDN-1 was downregulated, and the introduction of CLDN-1 retrovirus reduced the tumor aggressiveness and tumor migration ability and diminished micro-metastasis in the brain." (PMID 31952355, 2020). "On the other hand, claudin-1 expression is increased by PKC in melanoma cells and increased claudin-1 levels contribute to melanoma cell invasion and motility." (PMID 24009024, 2013). "Consequently, PKC-rich metastatic melanoma cells possess high nuclear Claudin-1, and PKA phosphorylation leads to the translocation of nuclear Claudin-1 to the cytoplasm." (PMID 35432533, 2022). "CLDN1 overexpression in brain metastasizing cells increases adhesion but reduces transmigration of melanoma cells through brain but not through lung endothelial monolayers." (PMID 32761606, 2021). "Such interactions do not occur in the lung where ECs do not express CLDN‐1 so that melanoma cells are not blocked from metastasis formation in the lungs." (PMID 32761606, 2021). "Similarly, claudin-1 expression induces MMP-2 activation, resulting in increased cell invasion and motility in melanoma cells." (PMID 24009024, 2013). "Interestingly, in melanoma, when claudin 1 was found in the nucleus it appeared to have no impact on invasion and metastasis." (PMID 26633531, 2015).
ovarian carcinoma (28 papers, 2008 to 2025). A malignant neoplasm originating from the surface ovarian epithelium. "In fact, TGF-β-induced cell migration is linked to the induction of CLDN1 expression in ovarian cancer cells." (PMID 36672179, 2023). "The upregulation of the CLDN-1 gene is found to be associated with ovarian cancer." (PMID 31952355, 2020). "In one particular study, the data of immuno-stains for claudin-1, -3, -4 and -7 on pleural effusions, corresponding primary tumors and solid metastasis of ovarian cancer were all gathered in order to identify associations between anatomic site, clinic-pathologic parameters and survival." (PMID 23685873, 2013). "Thus, we next sought to determine the association between LPA and claudin-1 in ovarian cancer cells." (PMID 19440550, 2009). "cDNA microarray analysis identified CLDN1 as one of the most significantly upregulated genes in ovarian cancer-initiating cells." (PMID 36672179, 2023). "This is also noted with CLDN1, with an increased promoter methylation-expression pattern in recurrent ovarian cancer, compared to the primary cancer." (PMID 36672179, 2023). "In the short- and long-term survivor (GSE51820) dataset from patients with post-chemotherapy ovarian carcinoma effusions, higher CLDN1 expression was correlated with shorter overall survival." (PMID 33828978, 2021). "Claudin-1 (CLDN1) methylation-expression relationships in matched primary-recurrent ovarian cancers and short (<3 years) versus long-term (>7 years) survivors." (PMID 33828978, 2021). "Eight genes were overexpressed in ovarian cancer samples compared with normal tissue samples and included CLDN1, CLDN3, CLDN4, CLDN6, CLDN7, CLDN9, CLDN10, and CLDN16." (PMID 34249076, 2021). "The role of CLDN-1 has been widely studied in two different types of ovarian cancers, namely, ovarian serous and ovarian endometroid carcinoma." (PMID 31952355, 2020). "The expression of CLDN-1 was shown to be negatively regulated by microRNA-155 (miR-155) which results in reduced proliferation and invasion of human ovarian cancer-initiating cells." (PMID 31952355, 2020). "Claudin-1 (CLDN-1) expression is downregulated by an increase of miR-155-5p in ovarian cancer cells." (PMID 31767859, 2019). "Over expression of miR-155 prevents tumorigenesis in human ovarian cancer mediated by down-regulation of claudin-1." (PMID 26061016, 2015). "Claudin-1 has been identified as one of the genes notably upregulated in ovarian cancer-initiating cells and claudin-1 overexpression in these cells leads to a low degree of cell differentiation and a high rate of invasive growth." (PMID 23685873, 2013). "To evaluate the role of claudin-1 in ovarian cancer cell migration, we performed a series of functional migration assays after manipulating claudin-1 expression in SKOV-3 cells using siRNA." (PMID 19440550, 2009). "Another independent study found claudin-1, claudin-3 and claudin-7 up-regulation together in ovarian cancer effusions predicts poor progression-free and overall survival." (PMID 19440550, 2009). "If we rationalize the data acquired in this study, what broader influence does the LPA-mediated increase in claudin-1 have during the progression of ovarian cancer?" (PMID 19440550, 2009). "Knockdown of claudin-1 expression in ovarian cancer cells reduces LPA-mediated cellular adhesion, enhances suspended cells and reduces LPA-mediated migration." (PMID 19440550, 2009). "Previous studies have shown that Claudin-1, Claudin-3, Claudin-4 and Claudin-7 proteins are highly expressed in ovarian carcinoma." (PMID 18781153, 2008). "For example, claudin-1 was decreased in pancreatic and ovarian cancers, as well as in LUAD." (PMID 38841188, 2024). "CLDN4 knockdown increased cellular accumulation and sensitivity to cisplatin, pointing towards the potential involvement of CLDN4 in platinum resistance in ovarian cancer, in line with the enhanced sensitivity toward carboplatin and paclitaxel upon CLDN1 knockdown in ovarian cancer cells." (PMID 36672179, 2023).